CTNNB1 (catenin beta 1)
Diseases named in the same sentence as CTNNB1 in open-access papers (continued):
Sharing a sentence is not in itself a finding about the gene and the disease.
Apert syndrome (1 paper, 2025). Apert syndrome (AS) is a frequent form of acrocephalosyndactyly, a group of inherited congenital malformation disorders, characterized by craniosynostosis, midface hypoplasia, and finger and toe anomalies and/or syndactyly. "In our reported case, the patient with Apert syndrome harbored both an oncogenic CTNNB1 variant and a pathogenic FGFR2 mutation." (PMID 40843798, 2025).
Arrhythmia (1 paper, 2022). Any cardiac rhythm other than the normal sinus rhythm.
Arthritis (1 paper, 2021). Inflammation of a joint. "In M1-polarizing conditions, 65–79*SE was predicted to stimulate activation of pro-inflammatory, pro-RA upstream regulators, such as Stat3, Rel, Rela, Jun, Ctnnb1 and Hif1a, among others, and to inhibit anti-arthritis or anti-inflammatory regulators (e.g. Klf2, Xbp1, Foxp3)." (PMID 33510427, 2021).
astrocytoma (1 paper, 2022). "Interestingly, there was a progressive increase in CTNNB1, which codes for β-catenin, according to astrocytoma malignancy grade, and its expression correlated significantly with LOXL1 and LOXL3 expression in both LGG-IDHmut and LGG-IDHwt." (PMID 36076905, 2022).
atypical polypoid adenomyoma (1 paper, 2022). An adenomyoma characterized by the presence of marked glandular architectural complexity. "In particular, CTNNB1 mutations are typically found in endometrioid histotype but not in serous histotype and are also observed in endometrioid intraepithelial neoplasia and atypical polypoid adenomyoma, which are regarded as precancerous lesions." (PMID 35034160, 2022).
basal cell neoplasm (1 paper, 2025). A neoplastic proliferation of basal cells in the epidermis (part of the skin) or other anatomic sites (most frequently the salivary glands). "Considering the low prevalence of β-catenin (+)/CTNNB1 wild-type BCAC, these tumors might tend to be more benign, or, in other words, non-invasive, than CTNNB1-driven basal cell neoplasms." (PMID 40360858, 2025).
benign gynecologic tumors (1 paper, 2025). "The best predictor of OC vs. benign gynecologic tumors was CTNNB1 expression (AUC = 0.95, accuracy = 0.86, sensitivity = 0.84, specificity = 1); however, the highest accuracy and sensitivity were detected by NOTCH2 (AUC = 0.89, accuracy = 0.89, sensitivity = 0.89, specificity = 0.89)." (PMID 40002854, 2025).
benign parathyroid tumor (1 paper, 2008). "Whether combined activity of two mutant S37A CTNNB1 alleles suffices for benign parathyroid tumor growth or whether constitutive WNT signaling is required in addition, remain to be investigated." (PMID 18541010, 2008).
Cachexia (1 paper, 2020). Severe weight loss, wasting of muscle, loss of appetite, and general debility related to a chronic disease. "Analysis of overlap of the leading edge genes revealed a large number of CTNNB1 target genes regulated by both GTx‐024 and cachexia versus tumor‐free controls but in different directions (n = 49 middle, 17 bottom left)." (PMID 31930715, 2020).
cervical tumors (1 paper, 2021).
chordoma (1 paper, 2023). Chordomas are rare malignant tumors arising from embryonic remnants of the notochord in axial skeleton.
cleft palate (1 paper, 2023). Cleft palate is a fissure type embryopathy that affects the soft and hard palate to varying degrees. "Another study suggested that the canonical Wnt signaling via ß-Catenin is responsible for the MEE-specific Tgfb3 gene expression, since deletion of the Ctnnb1 gene by a commonly used Keratin 14-Cre (K14Cre) mouse line almost completely abolished Tgfb3 expression in the MEE resulting in cleft palate." (PMID 37250135, 2023). "Among 64 K14Cre:Ctnnb1 mutants analyzed, only three of them displayed cleft palate." (PMID 37250135, 2023).
cystic neoplasm (1 paper, 2022). A benign or malignant neoplasm that contains a single or multiple cystic spaces. "With the aim of distinguishing MCNs from other PCNs, such as IPMN and SPN, some research have revealed that MCN is a kind of cystic neoplasm without the GNAS mutation and generally without the CTNNB1 mutation." (PMID 35299739, 2022).
cytomegalovirus infection (1 paper, 2025). A herpesvirus infection caused by Cytomegalovirus. "Rock2, Ccl5, Plk1, Rel, and Ctnnb1 are mainly associated with inflammatory responses, including positive regulation of IκB kinase/NF-κB signalling and human cytomegalovirus infection." (PMID 41007634, 2025).
desmoplastic fibroma (1 paper, 2020). A extremely rare bone tumor characterized by abundant collagen formation and a fibrous stroma, without evidence of mitosis or pleomorphism. "Limited data is available on the mutation status of CTNNB1specifically in desmoplastic fibroma of gnatic location, in one of two desmoplastic fibromas in the mandible, and a CTNNB1 mutation was detected." (PMID 31838586, 2020).
diabetic nephropathy (1 paper, 2011). "We assessed tag and potentially functional single nucleotide polymorphisms (SNPs; n = 31) in four key Wnt pathway genes (CTNNB1, AXIN2, LRP5 and LRP6) for association with diabetic nephropathy using a case-control design." (PMID 21876774, 2011). "Our results suggest that analysed common variants in CTNNB1, AXIN2, LRP5 and LRP6 are not strongly associated with diabetic nephropathy in type 1 diabetes among white individuals." (PMID 21876774, 2011).
DICER1 syndrome (1 paper, 2025). "Analogous to what occurred in this present tumor, however, a case of WDFA of the lung with coexistence of CTNNB1 and DICER1 mutations in a 16-year-old girl with a history of TFND, ovarian Sertoli-Leydig cell tumor, and familial DICER1 syndrome has been described." (PMID 40892116, 2025).
dyspraxia (1 paper, 2024). "In contrast to CTNNB1 syndrome, we did not detect oral–facial and mastication dyspraxia." (PMID 39336700, 2024).
E. coli infection (1 paper, 2015). "However RRMS clinic subtype patients also show an increase in the ACTB, KRT18, FYN, TUBA4A, NCL, CTNNB1 proteins which are a part of pathogenic E. coli infection pathway, which induce the mobilization of inflammatory cells." (PMID 25942430, 2015).
Endocrine Neoplasia (1 paper, 2025).
endometrial stromal tumor (1 paper, 2026). Neoplasms of the endometrial stroma that sometimes involve the myometrium. "This study adds to the growing body of evidence that CTNNB1 mutations represent a driver molecular event in a small subset of endometrial stromal tumors." (PMID 41606383, 2026). "Characterization and reporting of additional cases are needed to determine whether these are part of the spectrum of low-grade endometrial stromal tumors (either endometrial stromal nodule or LGESS) or represent a separate category of tumors characterized by CTNNB1 alteration as a driver event." (PMID 41606383, 2026).
eosinophilia (1 paper, 2025). "Interestingly, all and only the cases exhibiting cytoplasmic eosinophilia and enlarged nuclei harbored CTNNB1 c.101G > T; p.Gly34Val." (PMID 38418687, 2025).
esophageal squamous cell carcinoma (1 paper, 2020). Esophageal squamous cell carcinoma (ESCC) is a type of esophageal carcinoma (EC) that can affect any part of the esophagus, but is usually located in the upper or middle third. "In esophageal squamous cell carcinoma, SNHG12 regulates BMI1 expression via sponging miR‐6835‐3p and enhances CTNNB1 stability via recruiting IGF2BP2." (PMID 32239639, 2020).
esophageal tumor (1 paper, 2016). "Further studies are required to determine whether chromosomal losses occurred in the CDH1 and CTNNB1 loci in the esophageal tumor tissues that were examined in this study." (PMID 27600761, 2016).
esophagogastric adenocarcinoma (1 paper, 2022). "Notably, acquired mutation of CTNNB1 may drive immune checkpoint inhibitor (ICI)-acquired resistance in microsatellite instability (MSI)-high esophagogastric adenocarcinoma with BM." (PMID 36338733, 2022).
Failure to thrive (1 paper, 2023). Failure to thrive (FTT) refers to a child whose physical growth is substantially below the norm. "In accordance with previous studies reporting only one individual carrying a de novo splice mutation c.1081+1G>C in the intron 7 of the CTNNB1 gene and requiring prolonged enteral feeding due to severe failure to thrive, none of our patients required a G-tube placement." (PMID 37895192, 2023).
generalized dystonia (1 paper, 2022). "In eight patients with generalized dystonia from infancy, the mutation of PIGA, TCF4, CHRNG, SLC16A2, KCNQ2, NACC1, CTNNB1, or ARSA gene were found to be causative." (PMID 35719373, 2022).
gestational diabetes mellitus (1 paper, 2025). "Additionally, gestational diabetes mellitus may be linked to excessive CTNNB1 activation, which interferes with placental metabolic function and downregulates CDH1, thus disrupting placental barrier function." (PMID 40150405, 2025).
glaucoma (1 paper, 2025). Increased pressure in the eyeball due to obstruction of the outflow of aqueous humor. "CTNNB1’s repeated emergence across diverse analyses underscores its likely central role in modulating cellular responses associated with glaucoma." (PMID 41042282, 2025). "The connection between CTNNB1 and CYP39A1 is particularly intriguing given CTNNB1’s known role in the canonical Wnt signaling pathway—a pathway extensively linked to glaucoma through its regulation of cellular proliferation, differentiation, and survival processes." (PMID 41042282, 2025). "This potential mediator role implies that CTNNB1 could facilitate interactions or coordinate signaling among proteins involved in distinct yet related pathways, contributing to glaucoma pathology." (PMID 41042282, 2025).
glomus tumor (1 paper, 2019). A rare benign or malignant mesenchymal neoplasm arising from cells that resemble the modified smooth muscle cells of the glomus body. "However, glomus tumors lack β-catenin nuclear expression and CTNNB1 mutations." (PMID 30206803, 2019).
glycogen storage disease (1 paper, 2015). "Of note, H-HCA do not occur in patients with glycogen storage disease (GSD), neither are they associated with CTNNB1, IL6ST, GNAS, and STAT3 mutations." (PMID 26404250, 2015).
gout (1 paper, 2022). A condition characterized by painful swelling of the joints, which is caused by deposition of urate crystals. "The main corn silk compound, Mandenol, treated gout by targeting the Hippo signaling pathway through the CTNNB1, YWHAG, and YWHAZ proteins." (PMID 36276864, 2022). "The essential compound of corn silk is mandenol, which may target the hippo signaling pathway to treat gout through CTNNB1, YWHAG, and YWHAZ proteins." (PMID 36276864, 2022). "Our PPI analysis showed that turmeric and corn silk influence gout through their impact on a complex biological network, including HSPA1B, HSP90AB1, STUB1, CTNNB1, YWHAG, and YWHAZ." (PMID 36276864, 2022). "Mandenol, the corn silk compound, had high activity when docking with the target YWHAG and good activity when docking with the CTNNB1 and YWHAZ targets, suggesting that Mandenol may be an essential corn silk compound for gout." (PMID 36276864, 2022).
granulosa cell tumor (1 paper, 2014). A slow-growing, malignant tumor, characterize by the presence of granulosa-like cells and Call-Exner bodies, that is almost always found in the ovary. "While it has been reported that mice expressing constitutive activation of CTNNB1 in granulosa cells results in development of granulosa cell tumors, much remains unknown about the physiological significance of WNT/CTNNB1 in adult folliculogenesis." (PMID 24466091, 2014).
hemorrhage (1 paper, 2024). Loss of blood from the vascular compartment to the exterior or into nonvascular body space as a result of rupture or severance of the blood vessels. "Among the molecular subtypes, b-HCA with mutations in CTNNB1 exons 7 and 8 has the highest hemorrhage rate of 92%, followed by sh-HCA, which is associated with hemorrhage in 81% of the cases, while hemorrhage risk in b-HCAs with mutations in CTNNB1 exon 3 is 69%." (PMID 39061609, 2024).
Hyperglycemia (1 paper, 2021). An increased concentration of glucose in the blood. "Expression of CDH5, CTNNB1, and PRKCB was checked in the hyperglycemia disease model, and we observed that PRKCB was localized extensively in the membrane, while the signals of CDH5 and CTNNB1 were diffused and not exclusively on the membrane." (PMID 34180064, 2021).
Inguinal hernia (1 paper, 2020). Protrusion of the contents of the abdominal cavity through the inguinal canal. "Five essential proteins (PIK3R1, PTPN11, TGFBR1, CDC42, and SOS1) and three downstream common proteins (UBC, GRB2, and CTNNB1) were found to be related to inguinal hernia development." (PMID 31910207, 2020). "We discovered that PIK3R1, PTPN11, TGFBR1, CDC42, SOS1, and KRAS were the most essential inguinal hernia-causative proteins and UBC, GRB2, CTNNB1, HSP90AA1, CBL, PLCG1, and CRK were listed as the most commonly-involved downstream proteins." (PMID 31910207, 2020). "Most importantly, UBC, GRB2, and CTNNB1 were significantly enriched in the inguinal hernia PPI network." (PMID 31910207, 2020).
keloid (1 paper, 2025). An irregularly shaped, elevated mark on the skin caused by deposits of excessive amounts of collagen during wound healing. "For example, the SNHG1/miR-320b/CTNNB1 axis modulates fibroblast migration during keloid formation, while GNAS-AS1 knockdown reduces keloid growth via the miR-188-5p/RUNX2 pathway." (PMID 40943318, 2025).
lissencephaly type 2 (1 paper, 2025). "Taken together, the interplay of LIN28A and CTNNB1 resulted in a cortical migration disorder showing histomorphological and molecular similarities to human cobblestone lissencephaly (type 2) disorder." (PMID 40680886, 2025).
malignant glioma (1 paper, 2024). A grade III or grade IV glioma arising from the central nervous system. "In malignant gliomas, RBFOX2 acts as a reader, recognising hm5C introduced by NSUN5 and TET2 on CTNNB1 caRNA, leading to CTNNB1 caRNA degradation." (PMID 39243148, 2024).
melasma (1 paper, 2022). "Furthermore, CTNNB1 was linked to genes like DCT and HMGCS1, which were related to melanin biosynthetic process and lipid metabolic process reported in melasma study." (PMID 34609489, 2022).
mental disorder (1 paper, 2020). A disease that has its basis in the disruption of mental process. "The first was for the ST2-SC (CTNNB1) and the second was for ST3-TP (LNX1), indicating these two genes might be involved in the pathogenesis of five mental disorders during these two spatiotemporal points." (PMID 33371872, 2020).
mesenchymal tumors (1 paper, 2021). "However, mutations in β-catenin/CTNNB1, which are not uncommon in various cancer entities and in some mesenchymal tumors, are consistently absent in ILC." (PMID 34359596, 2021).
metaplastic carcinomas of the breast (1 paper, 2009). "Notably, genetic alterations in different members of the Wnt signaling pathway including CTNNB1 (β-catenin), APC, and WISP3 (Wnt1 Induced Secreted Protein 3) are relatively common among metaplastic carcinomas of the breast." (PMID 19578404, 2009).
metastatic melanoma (1 paper, 2021). A melanoma that has spread from its primary site to another anatomic site. "High-level SCNA profile in activating beta-catenin signaling pathway elements including CTNNB1, APC, and AXIN1-2 genes has been reported in metastatic melanoma but not in primary melanoma." (PMID 34026645, 2021).
Miscarriage (1 paper, 2024). A pregnancy that ends at a stage in which the fetus is incapable of surviving on its own, defined as the spontaneous loss of a fetus before the 22th week of pregnancy.
Moyamoya disease (1 paper, 2013). Moyamoya disease (MMD) is a rare intracranial arteriopathy involving progressive stenosis of the cerebral vasculature located at the base of the brain causing transient ischemic attacks or strokes. "Using the novel functional interpolating single-nucleotide polymorphisms bioinformatics approach, we identified 6 Moyamoya Disease-associated autoantibodies against APP, GPS1, STRA13, CTNNB1, ROR1 and EDIL3." (PMID 23518061, 2013).
mucinous adenocarcinoma (1 paper, 2023). An invasive adenocarcinoma composed of malignant glandular cells which contain intracytoplasmic mucin. "By histologic examination, oncogenic CTNNB1-altered LUADs generally displayed the features of conventional non-mucinous adenocarcinoma with predominant acinar (4/10), papillary (4/10), or solid (2/10) patterns." (PMID 37347751, 2023).
muscle atrophy (1 paper, 2023). The loss of muscle tissue due to inactivity or disease. "Our molecular docking results showed that Aloin A had good binding interactions with HSP90AA1, AKT1, CTNNB1, BCL2L1, RELA, TNF, AKT3, the ranging from −7.9 to −8.9 kcal/mol, suggesting that Aloin A stably combined with these proteins for attenuating cancer related muscle atrophy." (PMID 38180061, 2023).
Myocardial fibrosis (1 paper, 2025). "Stemness genes Ctnnb1 and Hifla, as well as oxidative phosphorylation and glutathione metabolism pathways, should be closely monitored in efforts to prevent myocardial fibrosis post-MI." (PMID 40595870, 2025). "Based on these findings, we hypothesize that Ctnnb1 may contribute to the detrimental effects of cardiac fibrosis post-MI, potentially aggravating the progression of myocardial fibrosis after injury." (PMID 40595870, 2025). "The key subgroup, C1 Postn + Fibroblasts, has the highest expression of Ctnnb1, suggesting that this gene may play a significant role in the progression of myocardial fibrosis after MI." (PMID 40595870, 2025).
nephrolithiasis (1 paper, 2024). The presence of a calculus in the pelvis of the kidney; this is most often composed of mineral salts and proteins. "Differential expression of AXL, HIP1R, JUP, CTNNB1, and DSG2 was confirmed via PRM, suggesting their potential roles in the development and advancement of nephrolithiasis, warranting further exploration." (PMID 39114033, 2024).
neuroblastoma (1 paper, 2022). Neuroblastoma (NB) is the most common solid, extracranial childhood tumor. "Studies have reported that PCF11 induces invasiveness in neuroblastoma through mediating WNT signaling via beta-catenin 1 (CTNNB1), subsequently activating PI3K/AKT that regulates, cell cycle progression, proliferation and apoptosis." (PMID 35756640, 2022).
neuroendocrine carcinoma (1 paper, 2023). A malignant neuroendocrine neoplasm composed of cells containing secretory granules that stain positive for NSE and chromogranin. "The second most frequently mutated gene in TCS is CTNNB1, encoding β-catenin and frequently co-occurring with SMARCA4 mutations in TCS and in SMARCA4-deficient carcinoma, olfactory carcinoma and neuroendocrine carcinomas." (PMID 38201285, 2023).